ERBB3 (erb-b2 receptor tyrosine kinase 3)
Description:
Tyrosine-protein kinase that plays an essential role as cell surface receptor for neuregulins. Binds to neuregulin-1 (NRG1) and is activated by it; ligand-binding increases phosphorylation on tyrosine residues and promotes its association with the p85 subunit of phosphatidylinositol 3-kinase. May also be activated by CSPG5. Involved in the regulation of myeloid cell differentiation.
Synonyms: HER3; ErbB-3; FERLK; LCCS2; MDA-BF-1; VSCN1; c-erbB-3; c-erbB3; erbB3-S; p180-ErbB3; p45-sErbB3; p85-sErbB3
Tractability: Small molecule: an approved drug acts on it; a structure with a bound ligand is known; a high-quality ligand is known; it has a high-quality binding pocket; it belongs to a druggable protein family. Antibody: a drug acting on it is in phase 2 or 3 trials; UniProt places it where antibodies can reach, with high confidence; its Gene Ontology location is reachable by antibodies, with high confidence; UniProt predicts a signal peptide or a membrane-spanning region; the Human Protein Atlas places it where antibodies can reach. PROTAC: its protein half-life has been measured; a small molecule that binds it is known. Other modalities: a drug acting on it is in phase 2 or 3 trials.
Target class: Kinase; Protein Kinase; Tyrosine protein kinase EGFR family; Enzyme; TK protein kinase group
Chemical probes: PD134466, PD134468, PD134469, PD134470, PD134471, PD134472, TX-85-1, TX2-121-1
Gene: Protein-coding gene on chromosome 12 (56,076,799 to 56,103,505, forward strand). Ensembl gene ENSG00000065361.
Subcellular location: Cell membrane (Isoform 1); Secreted (Isoform 2)
Subcellular location (Human Protein Atlas): Plasma membrane; Actin filaments; Predicted to be secreted
Pathways (Reactome):
Signal Transduction: Downregulation of ERBB2 signaling; Downregulation of ERBB2:ERBB3 signaling; ERBB2 Activates PTK6 Signaling; ERBB2 Regulates Cell Motility; GRB7 events in ERBB2 signaling; PI3K events in ERBB2 signaling; PI5P, PP2A and IER3 Regulate PI3K/AKT Signaling; PIP3 activates AKT signaling; RAF/MAP kinase cascade; SHC1 events in ERBB2 signaling; Signaling by ERBB2; Signaling by ERBB4
Disease: Constitutive Signaling by Aberrant PI3K in Cancer; Signaling by ERBB2 KD Mutants; Signaling by ERBB2 TMD/JMD mutants
Gene Ontology:
Molecular function: ErbB-3 class receptor binding; growth factor binding; identical protein binding; neuregulin binding; protein binding; protein heterodimerization activity; protein tyrosine kinase activator activity; protein tyrosine kinase activity; ubiquitin protein ligase binding; neuregulin receptor activity; transmembrane signaling receptor activity; ATP binding; protein kinase activity; signaling receptor activity
Biological process: cell surface receptor protein tyrosine kinase signaling pathway; extrinsic apoptotic signaling pathway in absence of ligand; negative regulation of cell adhesion; negative regulation of secretion; negative regulation of signal transduction; neuron apoptotic process; phosphatidylinositol 3-kinase/protein kinase B signal transduction; regulation of cell population proliferation; signal transduction; cranial nerve development; epidermal growth factor receptor signaling pathway; heart development; negative regulation of apoptotic process; negative regulation of neuron apoptotic process; neuron differentiation; peripheral nervous system development; positive regulation of epithelial cell proliferation; positive regulation of MAPK cascade; positive regulation of phosphatidylinositol 3-kinase/protein kinase B signal transduction; Schwann cell differentiation; wound healing; ERBB signaling pathway; ERBB2-ERBB3 signaling pathway; myelination; neuromuscular junction development; and 2 more
Cellular component: basolateral plasma membrane; ERBB3:ERBB2 complex; extracellular region; plasma membrane; receptor complex; basal plasma membrane; apical plasma membrane; lateral plasma membrane; membrane; postsynaptic membrane
Genetic constraint (gnomAD): Loss-of-function variants: 94 observed, 160.6 expected, observed/expected ratio (o/e) 0.59, 90% interval 0.49 to 0.69. The upper end of that interval is the gene's LOEUF score, 0.69, which puts it in group 2 of 6, group 1 being the genes least tolerant of losing a copy. Missense variants: 1,402 observed, 1,784.1 expected, observed/expected ratio (o/e) 0.79, 90% interval 0.75 to 0.82. Synonymous variants: 567 observed, 663.89 expected, observed/expected ratio (o/e) 0.85, 90% interval 0.8 to 0.92.
Cancer hallmarks: invasion and metastasis (promotes); proliferative signalling (promotes); escaping programmed cell death (promotes)
Homologues: Orthologues: macaque ERBB3 (99% identical), chimpanzee ERBB3 (99% identical), pig ERBB3 (94% identical), rabbit ERBB3 (94% identical), guinea pig ERBB3 (94% identical), mouse Erbb3 (91% identical), rat Erbb3 (91% identical), dog ERBB3 (90% identical), tropical clawed frog erbb3 (58% identical), zebrafish erbb3b (51% identical), zebrafish erbb3a (48% identical). Paralogues in human: ERBB4 (45% identical), EGFR (38% identical), ERBB2 (37% identical), INSR (14% identical), EPHA5 (14% identical), EPHA3 (14% identical), IGF1R (13% identical), EPHA6 (13% identical), EPHA4 (13% identical), EPHB1 (13% identical), KDR (13% identical), EPHA2 (13% identical), and 41 more.
Diseases named in the same sentence as ERBB3 in open-access papers:
ERBB3 is named in the same sentence as 313 diseases in open-access papers, as found by Europe PMC text mining. Sharing a sentence is not in itself a finding about the gene and the disease. The quoted sentences say what the papers report.
breast cancer (631 papers, 1992 to 2026). A primary or metastatic malignant neoplasm involving the breast. "Overall, 2 patients experienced partial response, 1 with EGFR-amplified glioblastoma and 1 with multiple brain metastases from ERBB2-amplified and ERBB3-mutated breast cancer." (PMID 38680990, 2024). "Both the systems caused efficient and persistent silencing of ErbB3 as marked by downregulation of its oncogenic signaling axis in in vitro breast cancer cells." (PMID 35806132, 2022). "shRNA mediated knock-down of Grhl2 in breast cancer cells caused the down-regulation of Erbb3 resulting in lowered levels of cell proliferation and changes associated with EMT." (PMID 35269877, 2022). "We demonstrate that the E1A coded by oAd/shErbB, in contrast to dAd/shErbB, caused downregulation of ErbB2 and ErbB3, yielding stronger downregulation of the ErbB3-oncogenic signaling axis in in vitro models of lung and breast cancer." (PMID 35806132, 2022). "Preclinical studies demonstrated that mutations in ERBB3 gene can promote oncogenesis in a ligand-independent manner in breast cancer (ВС)." (PMID 36517518, 2022). "ErbB3/Her3 expression appear to be linked to about 50–70% of lung, colorectal and breast carcinomas." (PMID 36498915, 2022). "We showed that HRG causes significant activation of P-Rex1 in breast cancer cells through activation of ErbB3." (PMID 27351228, 2016). "PKCα has been functionally associated with ErbB2, the main dimerization partner for ErbB3, and was found to be an essential mediator of ErbB2-driven breast cancer invasiveness." (PMID 27351228, 2016). "The main limitation of such approach is the rarity of ERBB2 and ERBB3 activating mutations among breast cancers." (PMID 27602491, 2016). "This is consistent with the well-established association of ErbB receptors, including ErbB3, with metastatic processes as well as with cytokine/pro-inflammatory pathways that play important roles in breast cancer progression." (PMID 27351228, 2016). "According to previous research, overexpression of EGFR, ERBB2, and ERBB3 is associated with poor prognosis and negatively correlated with estrogen receptor (ER) expression in breast cancer." (PMID 26907936, 2016). "ICGC data showed that, among breast cancers, ERBB3 activating mutations are predominantly found in ILC and / or triple negative breast carcinomas but remain a rare event in breast carcinomas." (PMID 27602491, 2016). "Heregulin (HRG), a growth factor highly expressed in mammary tumors, causes the activation of P-Rex1 and Rac1 in breast cancer cells via ErbB3, leading to a motile response." (PMID 27351228, 2016). "The validity of the ERBB3 sequencing method was successfully checked by sequencing the ERBB3-mutated breast cancer case (G284R) mentioned in the introduction and used as a positive control." (PMID 27602491, 2016). "Two factors were probably critical to thesuccess of the approach: the use of oncogenes commonly mutated or amplified inERα + breast cancer, and the use of culture medium favoring ERBB3 over EGFRsignaling to prevent squamous metaplasia invitro." (PMID 25527189, 2014). "Although dysregulation of ERBB3 and miRNAs is associated with tumorigenesis in human breast cancer, little is known about the natural miRNAs that act on ERBB3." (PMID 25248370, 2014). "Elevated expression of erbB3 protein has been reported in 50-70% of human breast cancers, and it seems to be associated with tumor size, metastasis, and recurrence." (PMID 24886126, 2014). "ERBB3 is frequently upregulated in breast cancer, and overexpression of ERBB3 is positively associated with metastasis, histological grade, tumor size and recurrence." (PMID 25248370, 2014). "We have reported that the underlying mechanism that elevated expression of erbB3 results in paclitaxel resistance in erbB2-overexpressing breast cancer cells is attributed to PI-3 K/Akt-dependent upregulation of Survivin." (PMID 24168763, 2013).
breast cancer (continued). "A role for erbB3 in breast cancer has only recently become appreciated, with overexpression of erbB3 shown to be positively associated with metastasis, increased histological grade and tumour recurrence." (PMID 21939528, 2011). "More recently, the other two members of the ErbB receptor family, ErbB3 and ErbB4, have been implicated in antihormone resistance in breast cancer." (PMID 21396094, 2011). "Changes in PR-A, SRC 1–3, erbB3, and Akt activity are consistent with increased cell proliferation and decreased apoptosis playing a role in mammary cancer susceptibility." (PMID 19590682, 2009). "We also found that the association between ErbB-3 and P-Akt positivity mainly occurs in ERβ1-negative breast cancer derived from patients with lower DFS indicating that both receptors are clinically relevant in predicting the response to Tamoxifen." (PMID 18270579, 2008). "Transgenic mice expressing the activated rat c-neu (with deletion mutations) bear mammary tumors with elevated co-expression of the mutant c-neu/ErbB2 and the endogenous mouse ErbB3-encoded protein." (PMID 16168116, 2005). "Patient 018 in cohort 4 had multiple sub-cm brain metastases from ERBB2-amplified and ERBB3-mutated breast cancer and was treated on study after receiving docetaxel, trastuzumab, and pertuzumab for primary and metastatic disease along with cerebellar radiation." (PMID 38680990, 2024). "For instance, the administration of NRG4 may yield beneficial cardiometabolic effects but simultaneously increase the risk of breast cancer development through prolonged activation of the receptors ErbB3 and ErbB4." (PMID 39872218, 2024). "Our group and others have shown that ErbB3, a tyrosine kinase receptor which can drive prostate and breast cell proliferation, is key target of NRDP1; decreased NRDP1 expression causes elevation of ErbB3 levels and can thereby increase prostate and breast cancer cell proliferation and survival." (PMID 34503235, 2021). "For example, circKRT19 expression derived from KRT19, a notch signaling regulator in breast cancer, is significantly associated with higher ERBB3 expression in mRNA (Wilcoxon rank-sum test, FDR < 2.2 × 10− 16) and protein levels (Wilcoxon rank-sum test, FDR = 7.91 × 10− 11)." (PMID 31446897, 2019). "Similarly, activating point mutations of ERBB3 have been described in 2013 and were found in vitro to display oncogenic activities in breast cancer cells." (PMID 27602491, 2016). "As stimulation of ErbB3 by HRG causes a prominent activation of Rac1 in luminal breast cancer cells via P-Rex1, leading to a motile response, we investigated how silencing P-Rex1 could affect the regulation of gene expression by this growth factor." (PMID 27351228, 2016). "Both ErbB2 overexpression and ErbB3 activation by HRG have been linked to breast cancer metastasis." (PMID 27351228, 2016). "That suppression of CD44 is able to deplete heregulin-induced activation of erbB signalling and also depletes HA-promoted erbB2:erbB3 association suggest a potential value of therapeutically targeting CD44 in breast cancer, potentially to improve the effect of current targeted therapies." (PMID 23039365, 2012). "Other evidences underline the importance of ErbB3 in HER2 addicted breast cancers." (PMID 22889873, 2012). "Immunoprecipitation and Western blot analysis were performed to examine whether IRS-1 associates with erbB receptors, notably erbB3, in the ER+ breast cancer cell lines." (PMID 21939528, 2011). "Heterodimers between these two receptors have been shown to form the most potent mitogenic and transforming receptor complex in vitro, and coexpression of erbB2 and erbB3 have been shown to be significantly associated with decreased survival in breast cancer patients." (PMID 21939528, 2011). "Second, expression of either ErbB2 or ErbB3 is associated with poor prognosis in breast cancer." (PMID 18841159, 2008).
breast cancer (continued). "Moreover, the loss of function of ERBB3 reduces the serum levels of PARK7 in breast cancer cells." (PMID 32357493, 2020). "EGFR (HER1) and ERBB2 (HER2) are frequently implicated in breast, lung, ovarian, and other malignancies, whereas ERBB3 (HER3) is commonly associated with breast cancer, and ERBB4 (HER4) has been detected in both breast cancer and granulosa cell tumors." (PMID 41230212, 2025). "With multiple HER3-directed antibody–drug conjugates already FDA-approved in breast cancer, a clear translational path exists for label expansion into PCa contingent on companion ERBB3 testing." (PMID 40806607, 2025). "Paradoxically, SET tumors retain active ERBB3 (HER3) signaling, a feature linked to autocrine growth loops in some HER2-negative breast cancers." (PMID 41155518, 2025). "In this system, the ErbB3 aptamer can specifically recognize and bind to the ErbB3 receptor overexpressed on the surface of breast cancer cells, realizing the precise delivery of siRNA." (PMID 40942197, 2025). "Elevated ERBB2 expressionis associated with breast tumor growth, and suppression ofERBB2 and ERBB3 induces apoptosis in breast cancer cells." (PMID 41541554, 2025). "ERBB3 coamplification/comutation was seen in ERBB2mut and ERBB2amp bladder cancer (9.9% and 7.8%, respectively), in ERBB2mut breast cancer (9.7%), and in ERBB2mut CRC (6.6%) but was more rare in other tumors." (PMID 40178042, 2025). "The tumor cells from both sexes had similar transcript levels of estrogen receptor alpha (Esr1), androgen receptor (Ar), and human epidermal growth factor receptors (Erbb2, Erbb3), which are the attributes of the Luminal B breast cancer subtype." (PMID 39684829, 2024). "Mutations of ERBB3 can induce activation of the MAPK pathway, and a previous case report showed that targeting ERBB3 G284R mutant breast cancer with trastuzumab plus lapatinib can lead to disease control." (PMID 38664720, 2024). "Genes identified in breast cancer included ERBB3, LIV‐1 and SLC44A4; in colorectal cancer CD71, PTK7 and SLC44A4; in lung cancer SLC44A4; in prostate cancer LIV‐1 and PSMA; and finally in stomach cancer CD71 and CD74." (PMID 37740463, 2023). "Upregulated genes ERBB3 (HER3) and ERBB4 (HER) belong to the HER family of receptors and are implicated in breast cancer." (PMID 37091785, 2023). "Within the 7 breast cancer cases, two cases showed a BRCA2 nonsense variant (p.R2318* and p.K3326*), one case showed ERBB3 G234R, one case showed KRAS G12V, and one case showed ARID1A P453fs." (PMID 36125633, 2023). "Overexpression of ERBB3 is also common in human breast cancers and likely enhances ERBB1-signaling, whereas both the overexpression and downregulation of ERBB4 expression has been reported in mammary tumors." (PMID 37219601, 2023). "In patients diagnosed with estrogen receptor (ER)-positive breast cancer, erbB3 upregulation occurs after treatment with fulvestrant, activating the MAPK/ERK pathway and leading to resistance to antiestrogen therapy." (PMID 36059813, 2022). "ERBB3 and ERBB2 levels are frequently associated, especially in human breast cancers, where ERBB3/ERBB2 heterodimers function as an oncogenic driver for breast tumor cell proliferation." (PMID 35406375, 2022). "Our study unveils a link between high ERBB3 expression and poor relapse-free patients’ survival in basal-like breast cancer patients." (PMID 35406375, 2022). "ERBB3 is involved in tumor development and progression of different cancer types, including breast cancer." (PMID 35406375, 2022). "In this study, we report an inverse correlation between ERBB3 mRNA expression levels and relapse-free survival in basal-like breast cancer patients." (PMID 35406375, 2022). "The similarity features enable this stacking model to provide interpretable knowledge about cancer, e.g. the role of ERBB3 in the MCF7 breast cancer cell line." (PMID 35933367, 2022).